CAV1 (caveolin 1)
Diseases named in the same sentence as CAV1 in open-access papers (continued):
Sharing a sentence is not in itself a finding about the gene and the disease.
tumor (continued). "As shown by Balliet and colleagues, the downregulation of mitochondrial transcription factor A (TFAM) in fibroblasts is linked to Cav-1 dysregulation, with a consequent induction of oxidative stress, mitochondrial dysfunction, and aerobic glycolysis in the tumour microenvironment." (PMID 29967776, 2018). "Ablation or mutation of Cav-1 is one of the features of fibroblasts in tumour tissues." (PMID 29967776, 2018). "Therefore, our study demonstrates that Cav-1 acts as a positive or negative regulator of the RAF-ERK feedback loop and that the mitogenic switch of Cav-1 function is highly associated with bidirectional alteration of its expression in tumor progression." (PMID 29141593, 2017). "Loss of stromal Cav1 expression in advanced tumor stages may thus contribute to resistance of these tumors to radiotherapy." (PMID 28112237, 2017). "In addition, the decreased expression of caveolin-1 in BC is significantly associated with advanced tumor stage, invasion or metastasis, early recurrence, and poor outcome." (PMID 29207674, 2017). "However, the molecular mechanism underlying the differential effects of Cav-1 on tumor growth has been poorly defined." (PMID 29141593, 2017). "The autophagic tumour stroma model proposes that loss of stromal CAV1 expression, and more specifically the loss of CAV1 expression of cancer-associated fibroblasts (CAFs), is the result of the overproduction of reactive oxygen species (ROS) by the cancer cells." (PMID 28515480, 2017). "Moreover, CAV1 knockout mice exhibit increased angiogenesis and predisposition to tumor proliferation, underscoring a role for CAV1 in tumor suppression." (PMID 28099944, 2017). "The CAV-1 rs3807987 polymorphism was observed to increase the risk of BC And the A allele of rs3807987 relates to a larger tumor size (≥2cm) and lower incidence of PR-positive BC while the AA genotype of rs7804372 associates with a higher ER and Her-2 positive rate among BC patients." (PMID 29207674, 2017). "Importantly, elevated CAV1 levels observed following drug exposure were associated with increased presence of tumor cells in ascites and metastasis in vivo." (PMID 29340103, 2017). "Pavlides and colleagues have demonstrated that Cav-1 loss could induce oxidative stress, mimic hypoxia, and drive inflammation in the tumor microenvironment." (PMID 28546853, 2017). "Furthermore, CAFs with loss of CAV1 expression have an increased ability to provide nutrients to cancer cells, and in this fashion, promote aggressive tumour growth." (PMID 28515480, 2017). "The PM protein Cav1 regulates tumor-associated cellular processes." (PMID 28913175, 2017). "Furthermore, CAFs in the tumor stroma exhibit robust activity in terms of aerobic glycolysis and autophagy due to loss of caveolin 1 (Cav-1) expression." (PMID 28279189, 2017). "Moreover, xenograft model experiments indicate that Cav-1 deficient stroma cells drive angiogenesis and tumor growth." (PMID 28915713, 2017). "The present findings show that high Cav-1 in tumor stroma is associated with a favourable outcome." (PMID 27764093, 2016). "Ablation or mutation of Cav-1 is one of the features of fibroblasts in tumor tissues." (PMID 26828520, 2016). "The reduction of Cav-1 in tumor stroma could therefore be related to loss of differentiated smooth muscle cells." (PMID 27764093, 2016). "Furthermore, ROS modulated Cav-1 expression is closely linked to the role of CAFs as tumor feeder and to biochemical remodelling of the microenvironment." (PMID 27595103, 2016). "In addition to its role as a tumor suppressor, Cav1 has also been linked to the regulation of focal adhesions and integrin-mediated actin remodeling." (PMID 26189182, 2015). "Furthermore, CAV1 promoter hypermethylation is significantly associated with the histopathological grade of the tumor." (PMID 26112043, 2015).
tumor (continued). "Increased cell motility coupled to reduced growth observed here in HNSCC cells expressing reduced Cav1 expression suggest that Cav1 expression in primary HNSCC might contribute to tumor growth, whereas its loss is a key factor in metastatic progression." (PMID 26474461, 2015). "In addition, higher tumor grade was significantly associated with increasing Cav-1 Allred score, indicating that Cav-1 is significantly up-regulated in more poorly differentiated tumors." (PMID 26065715, 2015). "On the basis of these observations we speculate that the loss of Cav1 in ECs might be responsible for the more pronounced tumor growth delay upon irradiation of MPR31-4 tumors grown on mice with stromal Cav1-deficiency." (PMID 25985209, 2015). "The association between RhoA/ROCK/Cav-1 and the genesis of tumor have raised increasing concerns." (PMID 26066055, 2015). "However, the expression, clinical roles and associated mechanisms of tumor Cav-1 expression are upregulated or decreased based on different cancer types or different experiments of a same cancer type." (PMID 25202343, 2014). "Also, loss of CAV1 leads to metabolic reprogramming of stromal cells to support the growth of adjacent tumor cells by delivering energy-rich metabolites and essential building blocks." (PMID 25328887, 2014). "Caveolae/lipid rafts are membrane-rich cholesterol domains endowed with several functions in signal transduction and caveolin-1 (Cav-1) has been reported to be implicated in regulating multiple cancer-associated processes, ranging from tumor growth to multidrug resistance and angiogenesis." (PMID 24738074, 2014). "In addition to the traditional roles of CAV1 in endocytosis, CAV1 has been implicated in processes ranging from signal transduction, to both oncogenesis, and tumor suppression." (PMID 25538703, 2014). "A new understanding of the role of the tumor microenvironment suggests that the loss of stromal caveolin-1 (Cav-1) as a key regulator may become a potential therapy target." (PMID 24949874, 2014). "In summary, CAV1, a membrane protein typically implicated in the formation of cell surface structures like caveolae and regulation of signalling, also plays a dual role in cancer, functioning as a tumor suppressor at early stages and a tumor promoter later on." (PMID 25328887, 2014). "The future will reveal how the seemingly opposing roles of autophagy in tumor development and progression are controlled, and to what extent the ambiguous role of CAV1 in cancer may be linked to the control of autophagy." (PMID 25328887, 2014). "This indicated that a loss of stromal Cav-1 may be a novel biomarker for aerobic glycolysis (the Warburg effect) in the tumor microenvironment." (PMID 25202343, 2014). "Tyrosine phosphorylated Cav1 (pY14Cav1), which is virtually extracaveolar, is associated with Rho activation and Src-dependent regulation of tumour cell motility, stabilization of focal adhesion kinases (FAK) within focal adhesions (FAs) and enhancement of tumour cell migration and invasion." (PMID 23521716, 2013). "Moreover, Cav-1 is implicated in the caveolin scaffolding domain and can induce inhibition of cytokine receptor signaling, suggesting the tumor suppressor role of Cav-1." (PMID 23527097, 2013). "A modification of this hypothesis suggests that loss of stroma Cav-1 increases autophagy in the tumor microenvironment leading to recycled nutrients that can be utilized by the tumor cells and protection of the tumor cells from apoptosis and autophagy." (PMID 22356861, 2012).
tumor (continued). "The association between loss of stromal Cav-1 and oxidative stress in the tumor stroma has also been confirmed by transcriptional profiling and bears a striking resemblance to the gene expression profiles of Alzheimer's disease (which is also directly linked to oxidative stress)." (PMID 21605374, 2011). "When stromal Cav-1 is lost in cancer associated fibroblasts (due to the onset of oxidative stress, hypoxia, and/or autophagy), this is highly predictive of tumor recurrence, metastasis, and drug-resistance." (PMID 21605374, 2011). "A loss of stromal Cav-1 also appears toplay a role in tumor initiation and progression." (PMID 20442453, 2010). "Disruption of caveolae activates MMP-2 in fibrosarcoma cells while Cav-1 overexpression in tumor cells causes decreased MMP-2 activity suggesting that Cav-1 may participate in the regulation of MMP-2." (PMID 20436850, 2009). "Distinct domains of caveolin-1 (phosphorylated Tyr-14 and Ser-80 or mutated Pro-132) may override the growth inhibitory activity of the caveolin-1 and lead to tumor cell invasion and metastases." (PMID 17764562, 2007). "Moreover, Cav1 loss in stromal cells, such as cancer-associated fibroblasts (CAFs), correlates with more aggressive cancer phenotypes, as it promotes the secretion of growth factors and cytokines that drive tumor growth and angiogenesis." (PMID 40963741, 2025). "Indeed, high expression of caveolin-1 in ECs decreased the efficacy of radiotherapy in a xenograft model of PCa, likely through hyperactivation of resistance mechanisms to radiation-induced apoptosis and stabilisation of the tumour-associated microvasculature." (PMID 36482187, 2023). "Besides, the gene encoding caveolin-1 is located at a putative tumor suppressor gene locus." (PMID 35064107, 2022). "Thus, it is important to dissect the characteristic stromal–epithelial CAV1 alterations within PCa, as a ‘simple’ CAV1-targeting would only achieve radiosensitization at the levels of tumor cells while a stromal CAV1 loss would counteract a desired therapeutic benefit." (PMID 35155239, 2022). "More specifically, decreased CAV1 expression in carcinoma-associated fibroblasts (CAFs) is sufficient to increase the intracellular levels of reactive oxygen species (ROS), promote autophagy and glycolysis, and diminish mitochondrial respiratory metabolism, thereby favoring tumor progression." (PMID 35740528, 2022). "Here, we determined whether tumor suppression by CAV1 is linked to modulation of the UPR." (PMID 32811828, 2020). "The binding of albumin to gp60 induces gp60 clustering and association with caveolin-1 (Cav-1), leading to the formation of caveolae that will carry the albumin complexes from the apical to the basal membrane, where the caveolae content is released into the tumor interstitium." (PMID 31858848, 2020). "However, the mechanisms underlying caveolin-1-mediated promotion of tumor invasiveness and angiogenesis remain unclear." (PMID 32676485, 2020). "Thus, in this study, we evaluate whether E-cadherin-independent tumor suppression by CAV1 might be linked to the ability of CAV1 to reduce S-nitrosylation and, hence, HIF1α activation in hypoxia." (PMID 32825247, 2020). "The ability of lovastatin in depleting CAV1 protein in a transient manner is also a potential pharmacological strategy in molecular imaging with antibody fragments and engineered variants because these biomolecules exhibit faster accumulation in the tumor tissue than do fully intact antibodies." (PMID 31171598, 2019). "The mechanisms by which this occurs are still in the early stages of investigation, although it has been noted that the tumor suppressive capabilities of Cx43 in keratinocytes may be linked to its interaction with caveolin 1, another factor associated with tumor suppression." (PMID 30622930, 2018).
tumor (continued). "Finally, in multidrug-resistant tumor cells, caveolae-associated caveolin-1, phospholipase D, chol and SM are upregulated, supporting the hypothesis that multidrug-resistance of tumor cells could partially result from lipid domain modifications." (PMID 30223513, 2018). "However, Cav-1 mutations were reported in certain tumor types." (PMID 29141593, 2017). "It is unclear how the observed loss of CAV1 and high glutamine availability work to drive tumour progression; however, the authors suggested that autophagy in the fibroblasts may serve as a key source of energy-rich glutamine to fuel mitochondrial activity in adjacent cancer cells." (PMID 27852311, 2016). "Moreover, radiation therapy reduced the overall Cav1 expression levels in MPR31-4 tumors grown in Cav1-proficient and Cav1-deficient mice, an effect which may be due to the impaired growth of Cav1-positive tumor cells after radiotherapy." (PMID 25985209, 2015). "Moreover, tumor growth delay after radiation was significantly increased in Cav1-deficient mice." (PMID 25985209, 2015). "However, Cav-1 may also directly affect tumor cells as transformation of NIH-3T3 cells with oncogenes such as H-Ras is associated with decreased Cav-1 expression and re-expression of Cav-1 can inhibit anchorage-independent growth of transformed NIH-3T3 cells." (PMID 22356861, 2012). "Caveolin-1 is a multifunctional scaffolding protein with multiple binding partners that regulates multiple cancer-associated processes including cellular transformation, tumor growth, cell death and survival, multidrug resistance, angiogenesis, cell migration and metastasis." (PMID 21471610, 2011). "The link between Cav-1 and these phenomena is confirmed by the observation that, the loss of Cav-1 in bone marrow-derived stromal cells from Cav-1 deficient mice, induces oxidative stress and mimics a pseudo-hypoxic state that leads to inflammation in the tumor stromal microenvironment." (PMID 21489269, 2011). "Thus, a loss of Cav-1 expression in cancer-associated myofibroblastsmay be a protein biomarker for oxidative stress, aerobic glycolysis, andinflammation, driving the "ReverseWarburg Effect" in the tumor micro-environmentand cancer cell metastasis." (PMID 20442453, 2010). "Moreover, integrin alpha 2 (ITGA2) is associated with caveolin-1 in tumor cells." (PMID 21209926, 2010). "However, a wealth of data is accumulating indicating that even in tissues where tumour formation is associated with an initial loss of caveolin-1, re-expression of the protein at later stages of tumour development correlates with more malignant tumour characteristics." (PMID 18400052, 2008). "Furthermore, caveolin-1 null mice are more susceptible to carcinogen-induced tumorigenesis, suggesting that caveolin-1 may be a tumor suppressor." (PMID 17331262, 2007). "Low shear stress in circulating tumor cells further boosts ROS-NO to stabilize Caveolin-1, suppressing ubiquitination and apoptosis." (PMID 41596231, 2026). "Their exosomes, enriched in tumor-promoting growth factor receptors, suppress Caveolin-1 in tumor cells and induce an EMT-like phenotype that fuels HNSCC growth." (PMID 41963732, 2026). "Pathway analysis of 3D tumour spheroids revealed miR-7, alone and in combination with lenvatinib, significantly reduced CAV1, IL8 and MMP-9 mRNA expression." (PMID 40715090, 2025). "To explore this mechanism, we selected PV-1, a tumor endothelial cell-specific marker, along with Caveolin-1, which is known to facilitate albumin endocytosis by endothelial cells, and SPARC, a protein that specifically binds to albumin." (PMID 40429837, 2025). "A study by Senetta identified Cav-1 expression as an independent prognostic marker in oligodendroglial tumors, correlating with higher tumor grades and reduced patient survival." (PMID 40243482, 2025). "Reports have assigned conflicting roles for CAV1 in cancer, acting both as a tumor suppressor and as an oncogene, depending on the type and stage of cancer." (PMID 41439026, 2025).
tumor (continued). "Further analysis of the bulk RNA-seq data (n = 55) showed significant upregulation of CAV1 in tumour tissues compared to matched normal tissues." (PMID 40715090, 2025). "In particular, CAV1 is a multifactorial scaffolding protein able to remodel the extracellular environment and is known to be involved in tumor progression." (PMID 39482470, 2025). "Regarding the expression of CAV1 in tumor cells, it has been alternately suggested that a high expression of CAV1 acts as a tumor‐promoting factor when expressed at high levels and as a tumor‐suppressing factor when expressed at low levels." (PMID 40419438, 2025). "The acellular 3D matrix generated by Cav‐1‐expressing fibroblasts is stiffer and more aligned than that of Cav‐1‐knockout fibroblasts, better stimulating tumor cell elongation, speed, and directional migration." (PMID 41377763, 2025). "CAV1 expression was also enriched within the stroma of recurrent disease implying CAV1’s role in establishing a tumour-permissive microenvironment." (PMID 40715090, 2025). "CAV1 expression was predominantly localized within tumor cells, with both phenotypic scores of these cells surpassing those observed in other cell types." (PMID 40180904, 2025). "Targeting Cav-1 in cancer cells and their EVs offers promising therapeutic opportunities, including inhibiting tumor growth, preventing metastasis, overcoming drug resistance, and improving overall patient outcomes." (PMID 40963741, 2025). "In ketogenic diet-fed tumor-bearing mouse models, we also observed a significant increase in lipid peroxidation and other related biomarkers, while CAV1 and SLC7A11 levels were markedly decreased compared to the normal diet group." (PMID 40180904, 2025). "The dual nature of Cav1, acting as both an oncogene and tumor suppressor depending on cancer type and stage, adds complexity to its therapeutic targeting." (PMID 40963741, 2025). "Increased Cav-1 expression was also associated with IDH wild-type status, higher histological tumor grade, and lower Karnofsky Performance Score." (PMID 40243482, 2025). "In further support, tumour-free mouse brain specimens show that CAV1 and HER3 coincide on the brain vasculature at discrete puncta resembling vesicles." (PMID 39984637, 2025). "Mechanistically, CD36 exerts its tumor‐suppressive effect by regulating the expression and activity of CAV1 via PPARγ, which increases intracellular lipid peroxidation and promotes ferroptosis in TNBC cells." (PMID 41267927, 2025). "In cancer, CAV1 exhibits striking context dependence: in some settings, it suppresses primary tumor growth, whereas in others, it enhances invasion and metastasis, depending on the cell type, stage, and microenvironment." (PMID 41374987, 2025). "In early-stage cancers, Cav1 often functions as a tumor suppressor by inhibiting cellular proliferation, promoting cell death through apoptosis, and maintaining cellular differentiation." (PMID 40963741, 2025). "Coculture with cancer cells shows that Cav‐1‐expressing fibroblasts significantly promote tumor cell invasion, which depends on Cav‐1‐regulated p190RhoGAP controlling Rho's downstream force‐dependent behavior." (PMID 41377763, 2025). "To assess the impact of ketone bodies on the CAV1 molecule in vivo, we established three tumor-bearing mouse models subjected to either a ketogenic diet or a normal diet." (PMID 40180904, 2025). "Knockdown of CAV1 in fibroblasts not only promoted tumour growth but also increased chemoresistance in PDAC and HCC." (PMID 39780187, 2025). "Spatial distribution of taurine metabolic genes (SLC27A5, CAV1) revealed pronounced heterogeneity, with tumor core regions exhibiting hyperactivation of taurine metabolism." (PMID 40630945, 2025).